IFT46 (intraflagellar transport 46)
Description:
Forms part of a complex involved in intraflagellar transport (IFT), the bi-directional movement of particles required for the assembly, maintenance and functioning of primary cilia. May play a role in chondrocyte maturation and skeletogenesis (By similarity).
Synonyms: C11orf2; C11orf60; FLJ21827; FAP32; CFAP32
Tractability: PROTAC: ubiquitination databases record sites on it.
Gene: Protein-coding gene on chromosome 11 (118,544,528 to 118,572,970, reverse strand). Ensembl gene ENSG00000118096.
Subcellular location: Cytoplasm, cytoskeleton, cilium basal body; Cell projection, cilium
Subcellular location (Human Protein Atlas): Actin filaments; Primary cilium; Principal piece
Pathways (Reactome):
Organelle biogenesis and maintenance: Intraflagellar transport
Gene Ontology:
Molecular function: protein binding
Biological process: cilium assembly; intraciliary anterograde transport; intraciliary transport; protein stabilization
Cellular component: cytoplasm; intraciliary transport particle A; intraciliary transport particle B; ciliary basal body; ciliary tip; cilium; microtubule organizing center; motile cilium; centrosome; plasma membrane bounded cell projection
Genetic constraint (gnomAD): Loss-of-function variants: 16 observed, 34.52 expected, observed/expected ratio (o/e) 0.46, 90% interval 0.31 to 0.7. The upper end of that interval is the gene's LOEUF score, 0.7, which puts it in group 2 of 6, group 1 being the genes least tolerant of losing a copy. Missense variants: 313 observed, 358.68 expected, observed/expected ratio (o/e) 0.87, 90% interval 0.8 to 0.96. Synonymous variants: 112 observed, 134.15 expected, observed/expected ratio (o/e) 0.83, 90% interval 0.71 to 0.98.
Homologues: Orthologues: macaque IFT46 (99% identical), pig IFT46 (96% identical), guinea pig IFT46 (96% identical), dog IFT46 (95% identical), mouse Ift46 (94% identical), rat Ift46 (94% identical), chimpanzee IFT46 (91% identical), zebrafish ift46 (71% identical), tropical clawed frog ift46 (70% identical), Caenorhabditis elegans dyf-6 (38% identical), Drosophila melanogaster IFT46 (31% identical).
Diseases named in the same sentence as IFT46 in open-access papers:
IFT46 is named in the same sentence as 6 diseases in open-access papers, as found by Europe PMC text mining. Sharing a sentence is not in itself a finding about the gene and the disease. The quoted sentences say what the papers report.
ciliopathies (2 papers, 2023 to 2025). "Our findings showed that the MTZ-treated transgenic embryos exhibited ciliopathy-like phenotypes such as cystic kidneys and pericardiac and periorbital edema, which are shown in IFT46 CRISPRant." (PMID 37363725, 2023). "We previously reported that IFT46 is expressed in ciliated organs during zebrafish early development and that knockdown of IFT46 exhibited ciliopathy-related phenotypes." (PMID 37363725, 2023). "Here, we introduce transgenic zebrafish lines under the control of ciliated cell-specific IFT46 promoter to recapitulate human ciliopathy-like phenotypes." (PMID 37363725, 2023). "In conclusion, we introduced the advantages of the Tg(IFT46:GAL4-VP16;UAS:nfsb-mCherry) line, which enables observation of ciliated cells and modeling for human ciliopathy." (PMID 37363725, 2023).
breast carcinoma (1 paper, 2014). "Among the 69 ciliary-associated genes analyzed, seven genes showed a statistically significant decrease in expression in breast cancers (log fold change: DYNC2H1 = -0.66; IFT46 = -1.07; PKD2 = -1.67; NPHP3 = -1.10; BBS2 = -1.51; BBS4 = -0.78; TTC8 = -1.46)." (PMID 24987519, 2014).
cystic kidneys (1 paper, 2023). "The IFT46 CRISPRants exhibit ventral body curvature, pericardiac and periorbital edema, and cystic kidneys (27%, n = 30/100) at 3 dpf." (PMID 37363725, 2023).
dementia (1 paper, 2024). Loss of intellectual abilities interfering with an individual's social and occupational functions. "Notably, IFT protein 46 (IFT46), a component of the IFT complex, was significantly increased in participants with “clinical dementia” (p = 0.020), accompanied by a significant positive correlation with DNALI1 (r = 0.46, p = 0.0019)." (PMID 38348540, 2024).
IFT46 also shares sentences with these, for which no sentence is quoted: COVID-19 (1 paper); genetic disease (1).